CRP (C-reactive protein)
Diseases named in the same sentence as CRP in open-access papers (continued):
Sharing a sentence is not in itself a finding about the gene and the disease.
thrombosis (continued). "The connection between thrombosis and inflammation in the development of venous thrombosis was validated by studies that observed an increase in plasma CRP levels in individuals with DVT compared with controls (2.5 mg/dL ± 3.2 vs. 1.0 mg/dL ± 2.5, p < 0.001)." (PMID 36611442, 2023). "He developed deep venous thrombosis during COVID-19 infection as well as pulmonary thromboembolism with biological markers of severity (increased D-dimers, CRP)." (PMID 37048757, 2023). "The results showed that the neutrophil and lymphocyte count and CRP, D-dimer, IL-6, integrin β1, integrin β2, and integrin β3 levels were all independent predictors of venous thrombosis." (PMID 37998519, 2023). "Among co-present thrombosis markers were elevated fg and accelerated ESR, and markers predictive of complicating thrombosis included elevated platelet count, CRP, DD-dimer, and ESR." (PMID 35275281, 2022). "High C-reactive protein to albumin ratio and D-dimer values were also predictive of thrombosis occurrence (p = 0.009, OR = 1.030, 95%CI 1.007‒1.052 and p = 0.002, OR = 1.016, 95%CI 1.006‒1.027, respectively)." (PMID 36028857, 2022). "The activated partial thromboplastin time (aPTT) was comparable between the groups, but D-dimer, fibrinogen and CRP were higher in the thrombosis group." (PMID 36248875, 2022). "Approximately 2 weeks after the start of risdiplam, an adult patient with SMA2 and pre-existing diverticulitis, deep vein thrombosis and pain, presented with fever, abdominal pain, two episodes of diarrhea, constipation and increased C-reactive protein levels." (PMID 35854272, 2022). "The univariate analysis revealed that an age > 60 years, hepatitis C, portal vein involvement (thrombosis), a tumor size > 5 cm, alpha-fetoprotein (AFP) > 400 ng/mL, serum albumin, and C-reactive protein (CRP) were risk factors for poor OS." (PMID 34067711, 2021). "The diagnostic accuracies of ALB, AGR, fibrinogen, and ESR were nearly identical (75%) and lower than that of CRP (91.67%) in patients with venous thrombosis." (PMID 34172035, 2021). "Univariate analysis demonstrated that age > 60 years, hepatitis C, portal vein involvement (thrombosis), tumor size > 5 cm, AFP > 400 ng/mL, serum albumin, and CRP were risk factors for poor OS." (PMID 34067711, 2021). "Levels of inflammation markers (neutrophil/lymphocyte ratio (NLR), platelet/lymphocyte ratio (PLR) and C-reactive protein (CRP)) were significantly higher in patients with thrombosis (p = 0.004, 0.02, 0.019, respectively)." (PMID 33563901, 2021). "Ascites, history of thrombosis and inflammatory markers such as CRP and leukocytes were similar between the groups, whereas esophageal varices was slightly more frequent in the cirrhosis group." (PMID 34504150, 2021). "Combined treatment of miR-136-5p agomir and oe-IL-6 or combined treatment of miR-136-5p agomir and oe-CRP led to complete venous thrombosis versus the combined treatment of miR-136-5p agomir and oe-NC." (PMID 33188660, 2020). "Lab studies demonstrated that increased CRP levels had an important role in appearance of venous thrombosis." (PMID 32168924, 2020). "More and more studies emphasize the role of inflammatory markers such as C-reactive protein and interleukin (IL)-1β, 6,8,10 in venous thrombosis." (PMID 32168924, 2020). "At diagnosis, 23/60 (38%) patients had effusions, 4/60 (7%) a thrombosis, and 37/54 (69%) elevated CRP." (PMID 30652419, 2019). "In patients who were free of DVT at the first examination, the mean C-reactive protein at the end of the second week was 153 ± 87 mg/l in patients who had a thrombosis at this second examination versus 82 ± 61 mg/l in patients still unaffected (P <0.005)." (PMID 23718723, 2013). "CC genotype showed the increased levels of both hs-CRP and IL-6 in thrombosis patients with positive history of infection." (PMID 24363620, 2013).
thrombosis (continued). "At the first examination, the mean C-reactive protein was 160 ± 89 mg/l in patients whose examination showed a thrombosis and 151 ± 79 mg/l in the other patients (P = NS)." (PMID 23718723, 2013). "Conversely, the Canakinumab Anti-inflammatory Thrombosis Outcomes Study demonstrated that interleukin-1β (IL-1β) antagonist canakinumab reduced the rate of recurrent CV events in patients with a prior MI and elevated hs-CRP levels." (PMID 40547439, 2025). "Elevated levels of CRP and calprotectin, both markers of inflammation, are also linked to thrombosis, but neither definitively indicates arterial versus venous thrombosis." (PMID 39661669, 2024). "Inflammatory biomarkers including CRP were found to be associated with VTE, but it was inconclusive that elevations in these biomarkers were from systemic inflammation or played an integral part in the formation of thrombosis." (PMID 39075344, 2024). "Sodium imbalance and prolonged increased C-reactive protein without signs of infections were significantly associated with the development of thrombosis." (PMID 38681768, 2024). "However, after adjusted analysis for inflammation (CRP) and thrombosis (D-dimer), surrogate laboratory variables, were significant risk factors for VTE development, explaining part of the mSOFA significance." (PMID 37187129, 2023). "The multivariate model, including mortality, length of stay, history of PE, peak ferritin, peak D-dimer, and peak CRP showed a history of PE (OR 6.80, 95%CI 1.18-39.34, p=0.032) and peak D dimer (OR 1.08, 95%CI 1.04-1.13, p<0.001) to be significant predictors of thrombosis in this population." (PMID 37575807, 2023). "The possibly raised D-Dimer levels in patients with venous thrombosis or coagulation disorder may alter our results and decrease the specificity of combination of CRP and D-Dimer." (PMID 35182199, 2023). "In cynomolgus experiments, it has been reported that blood cells, lactate dehydrogenase, and C-reactive protein are temporarily elevated in individuals with irreversible rejection, however, this is unknown in cases of graft failure due to vascular thrombosis." (PMID 36902818, 2023). "In multivariate analysis, peak D-dimer level and C-reactive protein to albumin ratio were poor prognostic factors for thrombosis occurrence (OR = 1.022, 95%CI 1.007‒1.038 and OR = 1.025, 95%CI 1.001‒1.051, respectively), while thromboprophylaxis use was protective (OR = 0.199, 95%CI 0.061‒0.645)." (PMID 36028857, 2022). "Interestingly, they found a correlation between YKL-40 and CRP and the JAK2V617F allele burden and thrombosis." (PMID 35626232, 2022). "The CANTOS (Canakinumab Anti-inflammatory Thrombosis Outcome Study) trial showed that the monoclonal antibody canakinumab directed against IL-1B was effective in reducing recurrent cardiovascular events in patients with prior MI and elevated CRP." (PMID 34722661, 2021). "Both elevated D-dimer and high CRP levels were associated with increased hospital mortality and a higher risk of VTE after adjusting for available confounders and for the known biological association between thrombosis and inflammation." (PMID 34909913, 2021). "Three studies have evaluated the prognostic role of CRP in patients with cancer-associated thrombosis (CAT) but none on a short-term basis." (PMID 33807848, 2021). "The results of this study show that CRP and D-dimer may be potential biomarkers of VTE recurrence after withdrawal of anticoagulation in patients with cancer-associated thrombosis." (PMID 32168924, 2020). "In univariate analysis, extra‐abdominal site, localized disease, no effusion or ascites only, absence of thrombosis, and normal CRP were associated with a significantly increased EFS." (PMID 30652419, 2019). "Moreover, patients in the high hs-CRP group suffered also from an excess of thrombosis (OR 2.57, 95% CI 1.39–4.75)." (PMID 28228104, 2017).
thrombosis (continued). "Although apo B and to a lesser extent apo A1 were associated with several hemostatic factors and CRP, none of these factors explained the association between these apolipoproteins and venous thrombosis risk." (PMID 28540474, 2017). "Meta-analysis of the association of albumin and CRP with AVF stenosis and thrombosis." (PMID 27458819, 2016). "However, analyzing the thrombo-pathological characteristics of patients with AIS who received RS vs. NRS showed significant differences in the expression of biomarkers associated with AIS and thrombosis, such as CD163, NET, and CRP, between the two patient groups." (PMID 41036279, 2025). "The CANTOS (Canakinumab Antiinflammatory Thrombosis Outcome Study) study demonstrated the clinical benefit of modulating interleukin-1β to reduce future atherosclerotic cardiovascular disease in patients with an elevated level of high-sensitivity c-reactive protein." (PMID 37380905, 2023). "The model showed, with an SE of 83% and an SP of 62%, that age; sex; levels of D-dimer, leucocytes, and IL6 collected at admission; and levels of CRP collected during the first 24 h of hospitalization could predict thrombosis with an accuracy of 77% (95% CI 69.9–84.0%)." (PMID 36835788, 2023). "Comparison included blood tests [C-reactive protein (CRP), albumin, and D-dimer], the incidence of deep vein thrombosis (DVT), range of motion (ROM), and clinical scores before and 1 year after surgery." (PMID 37106430, 2023). "DVT (deep vein thrombosis), CRP (C-reactive protein), BMI (body mass index), IQR (inter quartile range)." (PMID 37131204, 2023). "In the CANTOS trial (Canakinumab Anti-inflammatory Thrombosis Outcomes Study), a monoclonal antibody targeting IL-1β canakinumab was shown to reduce the level of the inflammatory marker C-reactive protein (CRP) and to reduce the cardiovascular risk, without influencing blood lipid profile." (PMID 32244740, 2020). "Additionally, CRP has been evaluated as a biomarker of acute VTE, and several studies have found an association between elevated CRP and the risk of venous thrombosis, although this finding was not universal." (PMID 32456008, 2020). "However, the combined use of endothelial biomarkers, C-reactive protein and D-dimer could be used to identify patient subsets with different frequencies of venous thrombosis." (PMID 25332871, 2014). "Venous thrombosis, arterial thrombosis, WBC, neutrophil, CRP, HbA1c, and PNI were found to be significant in the univariate analysis (p < 0.05 for all comparisons)." (PMID 38611651, 2024). "Inflammatory mediators, such as CRP, interleukins (IL-6 and IL-8), and tumor necrosis factor-alpha (TNF-α), play significant roles in both arterial and venous thrombosis." (PMID 39742171, 2024). "High-sensitivity C-reactive protein (hs-CRP), carotid intima-media thickness (CIMT), thrombosis, total antioxidant capacity (TAC), lipid profile, anthropometric indices, blood pressure, and quality of life were assessed before and after the intervention." (PMID 38082237, 2023). "The levels of CRP, IL-6, and integrins β1, β2, and β3 in patients with acute arteriovenous thrombosis were higher than those in the control group, suggesting that inflammation is involved in acute arteriovenous thrombosis and may represent a shared pathway between arterial and venous thrombosis." (PMID 37998519, 2023). "In this study, a retrospective analysis was made on the incidence of thrombosis and related laboratory data, including PLT, PT, APTT, DD, FDP and CRP." (PMID 36439504, 2022). "However, in our study, given their association with CRP, we cannot exclude the possibility that endothelial activation levels’ correlations with the clinical parameters of SSc and a history of thrombosis are explained by inflammation, rather than by direct causality." (PMID 36614946, 2022).
thrombosis (continued). "Third, persistently high coagulation potential by thrombin generation was lower after additional adjustment for serial C-reactive protein, anti-Xa level, fibrinogen, SOFA score, incident pulmonary embolism and deep venous thrombosis." (PMID 36277784, 2022). "The Canakinumab Antiinflammatory Thrombosis Outcome Study (CANTOS) trial showed that, among patients with prior AMI and hs-CRP ≥ 2 mg/L, treatment with a monoclonal antibody targeting interleukin-1β is associated with fewer cardiovascular events." (PMID 33081810, 2020). "In deep vein thrombosis (DVT), an inflammatory reaction triggers endothelial cell dysfunction and results in high serum concentrations of the inflammatory marker C-reactive protein." (PMID 24325351, 2013). "DEP also significantly increased plasma C-reactive protein (CRP) and TNF α concentrations, systolic blood pressure (SBP) as well as the pial arteriolar thrombosis." (PMID 22745783, 2012). "In addition, they found a statistically significant discrimination between controls and post-COVID cases using C-reactive protein (CRP), a blood biomarker that positively correlates with the incidence of thrombosis." (PMID 39337860, 2024). "However, the relationships between thrombosis and IL6 and CRP, which were included in the score, have been previously explored." (PMID 36835788, 2023). "In addition, C-reactive protein (CRP) is a widely used marker of inflammation, and elevated CRP levels are involved in the development and progression of thrombosis and CAD." (PMID 37924005, 2023). "The authors also analyzed C-reactive protein, fibrinogen, and platelets in patients with thrombosis versus those without thrombotic phenomena." (PMID 37187129, 2023). "On the other hand, the liver faces free-fatty-acid overflow, resulting in inflammation, as can be seen by the elevation of C-reactive protein (CRP) and in the activation of the coagulation system, indicated by increased fibrinogen, plasminogen activator inhibitor type 1 (PAI-1), and thrombosis." (PMID 35682865, 2022). "The Vienna Cancer and Thrombosis Study (CATS) evaluated potential risk biomarkers for the development of VTE in cancer patients, showing that CRP was not an independent predictive factor for VTE, but it was a predictor of mortality." (PMID 33807848, 2021). "DVT patients showed evidence for an acute phase reaction with increased serum C-reactive protein levels, but this was similar to many other patients admitted with suspected but not verified thrombosis." (PMID 25332871, 2014). "Finally, patients with thrombosis exhibited abnormal results in values of platelets, CRP and albumin more frequently than non-VTE patients." (PMID 38676874, 2024). "In our study, few children were obese, but CRP was still a risk factor for CRT, which might be related to the different characteristics of catheter-related thrombosis versus non-catheter-related thrombosis." (PMID 36864082, 2023). "However, in‐hospital rates of thrombosis were higher for COVID‐19 and the raised D‐dimer and CRP suggest that inflammation had not resolved at time of discharge." (PMID 37202865, 2023). "Thus, from the clinically and histopathologically demonstrated inflammation and necrosis in SINS, including vasculitis and thrombosis, and from the hypothesis that SINS is indirectly triggered by gut-derived MAMPs, an increase in CRP was expected." (PMID 35045844, 2022). "However, as none of the patients have thrombosis or embolism in the study, our results do not show that CRP and blood coagulation indexes are related with thrombosis and embolism." (PMID 33545964, 2021).
abscess (166 papers, 2006 to 2026). An inflammatory process characterized by the accumulation of pus within a newly formed tissue cavity which is the result of a bacterial, fungal, or parasitic infection or the presence of a foreign body. "In this large-scale cohort of MRI data from 535 patients with an acute neck infection, we show that high CRP (172 mg/L or higher), large abscesses (40 mm or larger), and RPE are significant risk factors for ICU admissions." (PMID 40236980, 2025). "In the testing dataset, comparable AUCs were obtained for high CRP (0.68), large abscess diameter (0.72), RPE (0.69), and risk score (0.81)." (PMID 40236980, 2025). "Manifestations of advanced cholecystitis like high CRP, gangrene of the gallbladder or abscess formation increase the risk of conversion to open cholecystectomy." (PMID 27891173, 2016). "•Risk score calculated from retropharyngeal edema, abscess size, CRP predicts ICU admissions." (PMID 40236980, 2025). "In patient 7, the increased CRP (60 mg/L) was associated with an anal abscess." (PMID 39156024, 2024). "In patients with neck infections of various etiologies, RPE was the strongest predictor of the need for intensive care unit (ICU) treatment with a nearly ten-fold increase in risk, even when other imaging outcomes (such as abscess size) and clinical variables (such as CRP) were taken into account." (PMID 36617619, 2023). "This score included 5 parameters that were significantly associated with abscess formation, such as ileo-colonic location of the disease, perianal CD, neutrophil-to-lymphocyte ratio, and CRP level, whereas the current use of corticosteroids was negatively associated with abscess formation." (PMID 33971899, 2021). "Advanced cholecystitis with high CRP, gangrene or an abscess increase the risk of conversion." (PMID 27891173, 2016). "Lower eGFR (p < 0.001) and higher C‐reactive protein (CRP) (p = 0.013) were also observed in the abscess group." (PMID 40046517, 2025). "Significant predictors for ICU admission were RPE, maximal abscess diameter (≥40 mm), and C-reactive protein (CRP) (≥172 mg/L)." (PMID 40236980, 2025). "The eradication phase begins when the patient is hemodynamically stable, the C-reactive protein (CRP) levels have fallen, and any abscesses or deep-seated infections have significantly improved or been resolved." (PMID 40149115, 2025). "The cut-off points calculated from ROC curves with the Youden method for large abscess diameter and high CRP were 39.5 mm and 171.5 mg/L, respectively." (PMID 40236980, 2025). "In various studies, it is observed that the C-reactive protein value is significantly higher in patients with multiple abscesses in different cervical spaces." (PMID 40005441, 2025). "RPE, maximal abscess diameter, and CRP were identified using multivariate binary logistic regression as statistically significant independent predictors for ICU admissions." (PMID 40236980, 2025). "In conclusion, we propose a combined risk score based on CRP, RPE, and maximal abscess diameter, predicting ICU admissions on acute neck infection patients with 80 % accuracy and 95 % NPV." (PMID 40236980, 2025). "Our findings suggest that DNI patients exhibit significantly lower HALP scores compared with controls, correlating with higher CRP levels, larger abscess size, and prolonged hospitalization." (PMID 40686698, 2025). "Fever was the primary symptom in both left- and right-lobe abscesses, with elevated levels of white blood cell count, procalcitonin, and C-reactive protein." (PMID 41574288, 2025). "The risk score (0−7) (AUC=0.82, 95 % confidence interval [CI] 0.77–0.88) outperformed CRP (AUC=0.73, 95 % CI 0.66–0.80, p = 0.001), maximal abscess diameter (AUC=0.72, 95 % CI 0.64–0.80, p < 0.001), and RPE (AUC=0.71, 95 % CI 0.65–0.77, p < 0.001)." (PMID 40236980, 2025). "The predictive abilities of white blood cell (WBC) count and CRP at different timepoints (on admission, d 3, and d 5) for residual abscesses were evaluated." (PMID 40046517, 2025).